NUPR1 (nuclear protein 1, transcriptional regulator)
Diseases named in the same sentence as NUPR1 in open-access papers (continued):
Sharing a sentence is not in itself a finding about the gene and the disease.
cancer (continued). "However, studies carried out with previous compounds (TFP, ZZW-115 and its first series of derivatives) on NUPR1-deficient mice did not result in the inhibition of cancer growth, suggesting that the main target for these drugs is in fact NUPR1." (PMID 34680086, 2021). "Therefore, NUPR1 is a promising therapeutic target for developing new cancer therapies." (PMID 34030133, 2021). "Thus, inhibition of the protein–protein interaction between NUPR1 and karyopherin β1 by small molecules is a candidate drug combination strategy that may be broadly applicable in cancer therapeutics." (PMID 33801927, 2021). "However, NUPR1 has multiple functions and may be a double-edged knife with the ability to suppress tumors and promote tumor development in a variety of cancers." (PMID 33920455, 2021). "Thus, NUPR1 is present at correspondingly higher levels in cancer cells." (PMID 34359572, 2021). "Our data support the idea that NUPR1 activation is strongly involved in protecting the cell against programmed cell death by both apoptosis and programmed necrosis, and therefore, targeting NUPR1 protein in cancer appears to be a promising tool as an anticancer therapeutic strategy." (PMID 30451898, 2018). "Therefore, induction of Nupr1 expression might play important roles in chromium-induced cancer development." (PMID 27285315, 2016). "In addition to its role in cellular stress, NUPR1 is overexpressed in several types of human cancers, namely in the late stages and metastasis of pancreatic cancer, which is relevant to the fact that pancreatic ductal adenocarcinoma displays outstanding resistance to cell stress." (PMID 25056123, 2014). "It has been demonstrated that NUPR1 binds to poly [ADP-ribose] polymerase 1 (PARP1) and inhibits the activity of PARP1 in cancer cells." (PMID 39991577, 2025). "Analysis of data from 33 common cancers in the TCGA database revealed that the genes HLF, HPCAL1, and NUPR1 exhibit significant differential expression between tumor and normal tissues in LUAD and several other cancers." (PMID 40421217, 2025). "Recently, we identified LZX-2-73 as a promising drug candidate with potent anticancer activity, targeting the nuclear protein 1 (NUPR1), an emerging and promising target in cancer therapy." (PMID 41249113, 2025). "Genetic inhibition of NUPR1 induces PARP1 over-activation and decreases ATP production and cell viability in cancer cells." (PMID 39991577, 2025). "To demonstrate that NUPR1 presence in EVs is not limited to TNBC cells, we analyzed NUPR1 expression in EVs from another cancer type." (PMID 38405101, 2024). "The expression of nuclear protein-1 (NUPR1), an ER-stress response factor that plays an important role in cell proliferation, migration, and reactive oxygen species (ROS) generation in cancer cells, significantly reduced in HERV-K env KO cells." (PMID 33920455, 2021). "Nuclear protein 1 (NUPR1) is activated in cellular stress and is expressed at high levels in cancer cells." (PMID 34359572, 2021). "As NUPR1 is involved in DNA-damage stimulus processes, we had shown in our previous work that treatment with ZZW-115 sensitizes cancer cells to genotoxic-induced DNA damage." (PMID 34680086, 2021). "Our latest research also found that by downregulating the expression of GSH-related genes, the NUPR1 inhibitor ZZW-115 affects the antioxidant system and promotes ferroptosis in cancer cells." (PMID 34359572, 2021). "Altogether, these data indicate that NUPR1 inactivation with ZZW-115 is a promising anticancer strategy for PDAC, but also other cancers, and therefore to characterize its mechanism of action is clinically relevant." (PMID 34599149, 2021).
cancer (continued). "Nuclear protein 1 (NUPR1) is a transcriptional regulator involved in stress response and was found to be overexpressed in a number of cancer entities as well as to play important roles in tumor progression and metastasis." (PMID 32674264, 2020). "The best compound (that with the largest affinity for NUPR1, and within the same order than that of NUPR1 for its natural partners), ZZW-115, kills different kinds of cancer cells with IC50 values ranging from 0.84 to 4.93 μM." (PMID 31667555, 2020). "In addition, Nupr1 might have impact on metastasis of cancers." (PMID 27285315, 2016). "These considerations raise optimism that this knowledge will fuel future studies aimed at shedding light onto the function of Nupr1 as a regulator of OIS in other organs and consequently have an impact on cancer development." (PMID 24902898, 2014). "Western blot analysis confirmed significantly lower expression levels of HLF, NUPR1, and HPCAL1 in NCI-H1975 and A549 cancer cells (p < 0.05), suggesting these genes may be involved in the development of LUAD." (PMID 40421217, 2025). "Subsequent research has revealed that NUPR1 is widely expressed in various cancer tissues, while it remains absent in healthy, unstressed cells." (PMID 41249113, 2025). "Analysis of RNA‐sequencing (RNA‐seq) data from The cancer genome atlas (TCGA), gene expression omnibus (GEO) databases, and international cancer genome consortium (ICGC) revealed that the NUPR1+ macrophage signature was significantly enriched in tumor tissues compared to adjacent normal tissues." (PMID 40305758, 2025). "The TCGA and GEO datasets (GSE51985) showed there was no upregulation of NUPR1 in primary cancer tissues compared to adjacent normal tissues." (PMID 39085744, 2025). "Therefore, to explore the protein expression of NUPR1 in LUAD patients, IHC analysis was performed at Nantong Cancer Hospital." (PMID 38167084, 2024). "The expression of NUPR1 in T3 and T4 BLCA was higher than that in T1 and T2 cancer (p < 0.001)." (PMID 36468653, 2023). "Numerous types of tumors may share similar genetic or molecular features, there are a lot of studies showed that NUPR1 and TRIB3 are involved in cancer biology, and we think this prognosis model that includes these genes may be applied to more types of tumors." (PMID 37626099, 2023). "At the same time, the inactivation of NUPR1 reduced the expression of the tricarboxylic acid cycle (TCA) genes and activated glycolysis genes, thereby promoting a strong metabolic reprogramming in cancer cells." (PMID 34359572, 2021). "Thus, we concluded that NUPR1 is involved in the DDR and that ZZW-115 targeting of NUPR1 sensitizes cancer cells to any genotoxic treatment." (PMID 32780723, 2020). "Here, we propose that specific inhibition of NUPR1 function by ZZW-115 displayed a strong potentiating effect of several genotoxic agents and on diverse cancer cell types by directly impairing the SUMOylation of the proper function of the major DNA repair actors or their molecular partners." (PMID 32780723, 2020). "Interestingly, we also show that seven major gene regulators (TP73, RICTOR, NUPR1, NKX2‐3, MYCN, IL10, and EPO) involved in inflammation, oxidative stress, DNA damage, and cancer processes were affected by MP radiation." (PMID 29786969, 2018).
cancer (continued). "We posited that TNBC progression was independent of the IFN1 signaling but was mediated through NUPR1 packaged within cancer cell-derived EVs and that reserpine functioned in limiting NUPR1 packaging into EVs and suppressed NUPR1 expression in recipient cells treated with EVs." (PMID 38405101, 2024). "In this experiment, the expression of MFSD12 and NUPR1 mRNA in the L. acidophilus KLDS1.0901 treatment group was lower than that of nontreated cells, indicating that low MFSD12 and NUPR1 are related to inhibiting cancer cell proliferation and promoting apoptosis." (PMID 35250903, 2021). "NUPR1 is over-expressed in almost any, if not all, cancer tissues." (PMID 34680086, 2021). "Hence, one advantage of a compound like ZZW-115 is that it potentiates the effect of genotoxic agents by targeting a stress-induced protein, NUPR1, which is abnormally present in many cancer cells but almost absent from normal cells." (PMID 32780723, 2020). "NUPR1 (UniProtKB O60356) is an 82-residue-long (8 kDa), highly basic, monomeric IDP that is overexpressed during the acute phase of pancreatitis and in almost any, if not all, cancer tissues." (PMID 32933064, 2020). "NUPR1 is an 82-residue-long, monomeric, basic and intrinsically disordered protein (IDP), which was found to be invariably overexpressed in some, if not all, cancer tissues." (PMID 31744261, 2019). "Among these molecules, ZZW-115 was the most efficient, as it displayed the best affinity for NUPR1 in vitro and showed antitumoral activity 10 times higher than TFP when tested on a large panel of primary PDAC-derived cells and several nonpancreatic cancer cells." (PMID 32780723, 2020).
tumor (84 papers, 2010 to 2026). "NUPR1 is highly expressed in tumor-associated macrophages within HCC and is related to immunosuppressive polarization and poor immunotherapeutic response, suggesting its potential as a biomarker and therapeutic target in HCC." (PMID 41153430, 2025). "This study investigates the role of nuclear protein 1 (NUPR1), a gene prominently expressed in tumor‐associated macrophages (TAMs), in mediating this suppression and influencing immunotherapy outcomes." (PMID 40305758, 2025). "Nuclear protein 1 (NUPR1) is highly expressed in tumor-associated macrophages (TAMs) and is crucial for immunosuppression and immunotherapy outcomes in HCC." (PMID 40867622, 2025). "Some of these, such as PEG3 and NUPR1, have been individually implicated in neuronal survival and tumor suppression, respectively." (PMID 40595248, 2025). "The expression of NUPR1 was highly correlated with tumor‐associated macrophage markers including CCL2, CCR5, CD80, and CD86." (PMID 36468653, 2023). "On the other hand, in domain 4, we observed upregulation of KRT8, AQP3, KLHDC7B and CDH1, which tend to exhibit stronger tumor progression and metastasis, and high expression of genes NUPR1 and DBI associated with chemotherapy resistance." (PMID 36250636, 2022). "NUPR1, a DNA-binding protein associated with cell cycle regulation and apoptosis, has been shown to be involved in tumor progression." (PMID 33408794, 2021). "Nupr1 has also been implicated in mediating cannabinoid-induced apoptosis of tumor cells through upregulation of the ERS-related genes ATF4, Chop and Trib3 (tribbles pseudokinase 3)." (PMID 27031958, 2016). "Noteworthy events include upregulation of apoptosis (Bcl)-related gene Bid3 and downregulation of Cav2 tumor suppressor and metastasis-linked Nupr1." (PMID 22260314, 2012). "Furthermore, APOE, APOC1, C1QA, C1QB, and NUPR1 are indicative markers of variations in the infiltration of tumor-associated macrophages (TAM), where TAM infiltration is known to be associated with unfavorable survival outcomes in solid tumors." (PMID 38783355, 2024). "The expression of NUPR1 was highly correlated with tumor‐associated macrophage markers including C‐C motif chemokine ligand 2 (CCL2, R = 0.392, p < 0.001), C‐C chemokine receptor type 5 (CCR5, R = 0.323, p < 0.001), CD80 (R = 0.302, p < 0.001), and CD86 (R = 0.381, p < 0.001)." (PMID 36468653, 2023). "Our results revealed that the expression level of NUPR1 may be involved in the polarization of macrophages to tumor‐associated macrophages." (PMID 36468653, 2023). "Beyond tumor-intrinsic roles, NUPR1 remodels the tumor microenvironment by driving immunosuppressive macrophage polarization and amplifying inflammatory signaling, collectively sustaining a pro-survival niche." (PMID 42104400, 2026). "The tumor site demonstrated a weak inverse correlation with NUPR1 promoter methylation (r = −0.12) and weak positive correlations with GLI1 (r = 0.22) and NDRG2 (r = 0.19) promoter methylation." (PMID 41596413, 2026). "Here, we synthesize evidence positioning NUPR1 as a central node of tumor adaptation that integrates metabolic rewiring, proteostatic balance, and cell-death checkpoints into a unified stress-response framework." (PMID 42104400, 2026). "In TNBC, which lacks targeted therapies and relies primarily on chemotherapy, NUPR1 plays an integral role in tumor progression, therapy resistance, and poor clinical outcomes." (PMID 41429768, 2025). "Tumor-derived lactate boosts NUPR1 in macrophages via histone lactylation, creating a feedback loop that worsens immune suppression." (PMID 40867622, 2025). "report that tumor‐derived lactate induces NUPR1 expression via H3K18 lactylation, which can promote the pro‐tumor M2 macrophage polarization through ERK and JNK signaling pathways." (PMID 40305758, 2025).
tumor (continued). "Transcriptional co-regulator nuclear protein 1 (NUPR1) has been identified as a key stress-adaptive disordered protein that promotes tumor progression and therapy-induced resistance." (PMID 41429768, 2025). "First, while we employed a selective inhibitor of NUPR1 for in vivo experiments, NUPR1 is also expressed at varying levels in other immune cells and tumor cells." (PMID 40305758, 2025). "In contrast, TCM from tumor cells treated with Oxamate or 2‐Deoxy‐D‐glucose (2‐DG), both of which inhibit glycolysis, resulted in a suppression of NUPR1 expression and histone lactylation in THP1 cells." (PMID 40305758, 2025). "Subsequent experiments demonstrated that tumor‐derived supernatants upregulate NUPR1 expression in macrophages while inhibiting tumor cell glycolysis markedly reduced the supernatant's ability to induce NUPR1 expression in macrophages." (PMID 40305758, 2025). "Correlation analysis revealed a significant positive correlation between lactate levels and the expression of both CD206 and NUPR1 in the tumor tissue." (PMID 40305758, 2025). "The results demonstrated that tumors in mice receiving TFP‐2HCL‐treated BMDMs were significantly smaller than those in the control group, indicating that NUPR1 inhibition in macrophages suppresses tumor growth in vivo." (PMID 40305758, 2025). "Analysis of bulk RNA‐seq, scRNA‐seq and ST data confirmed that NUPR1 was significantly higher in macrophages within the TME compared to non‐tumor tissues." (PMID 40305758, 2025). "Nuclear protein 1 (NUPR1), a stress-inducible transcriptional regulator, is upregulated in various tumor entities and is associated with therapy resistance, promoting cell survival under metabolic and genotoxic stress conditions." (PMID 40707944, 2025). "In vivo validation using a 4T1 cell-derived fully immunocompetent murine model further established its therapeutic efficacy, with significant reductions in tumor size, NUPR1 expression, and cell proliferation." (PMID 41429768, 2025). "Collectively, these findings demonstrate that tumor‐derived lactate upregulated histone lactylation levels, thereby driving the expression of NUPR1 in macrophages." (PMID 40305758, 2025). "In summary, our studies demonstrate that concurrent administration of PD‐1 mAb and pharmacological targeting of NUPR1 effectively remodel the tumor immune microenvironment, reduce macrophage‐mediated immune suppression, and promote tumor regression." (PMID 40305758, 2025). "Patients with elevated NUPR1 expression in macrophages also exhibited higher glycolysis scores in tumor cells than those with lower NUPR1 expression." (PMID 40305758, 2025). "In contrast, NUPR1 exhibits tumor-suppressive properties in PCa by downregulating key oncogenic pathways, inhibiting tumor cell proliferation and survival, and inducing apoptosis in response to cellular stress." (PMID 40707944, 2025). "What's more, we validated our results in the subcutaneous tumour model and found a consistent increase of NUPR1 in RR cells." (PMID 40176685, 2025). "Studies have shown that Nupr1 plays an upstream role in ER stress response during tetracycline-induced apoptosis in mouse and human tumor cells." (PMID 38347241, 2024). "Previous studies have shown that the role of Nupr1 is upstream of ER stress response in the tetracycline-induced apoptosis of mouse and human tumor cells." (PMID 38347241, 2024). "In a tissue microarray (TMA) of TNBC patient tissues (n=130), we verified that, as tumor grade increased, NUPR1 expression increased and HDAC11 expression decreased." (PMID 38536720, 2024). "Treatment with ZZW-115, an NUPR1 inhibitor, reversed the tumor-promoting effects of circPIAS1 and sensitized HCC cells to lenvatinib." (PMID 38802795, 2024). "(F) Reverse transcriptase-quantitative polymerase chain reaction (RT-qPCR) analysis of NUPR1 mRNA expression in cells (left) and tumor tissue from a mouse xenograft." (PMID 38536720, 2024).